TNF (tumor necrosis factor)
Diseases named in the same sentence as TNF in open-access papers (continued):
Sharing a sentence is not in itself a finding about the gene and the disease.
cancer (continued). "For instance, TNF proved to have potent tumoricidal activity in vitro and in mouse models in initial studies, a finding that sparked interest in the development of TNF for cancer therapy." (PMID 23840967, 2013). "Previous studies have indicated that Cygb loss was associated with increased cancer cell proliferation and overexpression of IL-1, IL-6, VEGF, TNFα, and TNFb mRNAs in cancer development in the liver and lungs of mice exposed to N,N-diethylnitrosamine." (PMID 23688241, 2013). "A functional polymorphism, -308 G>A (rs1800629), which is located in the promoter of TNFA gene, has been suggested to alter the production of TNF-α and influence cancer risk." (PMID 23326309, 2013). "Associated molecular mechanisms relied on an inhibition of the NF-κB system as already described in vitro in LPS treated macrophages or TNFα treated cancer cells." (PMID 23861901, 2013). "Taken together, these studies suggest a pivotal role of TNF-α in lung complications resulting from cancer treatment." (PMID 23468959, 2013). "Among the panoply of inflammatory mediators, nuclear factor kappaB (NF-kB) and tumor necrosis factor-α (TNF-α) are the key factors involved in cancer-related inflammation." (PMID 23457494, 2013). "Chemotherapeutic agents kill cancer cells and these treatments trigger a parallel stromal reaction by releasing TNF-alpha by endothelial cells and pericytes." (PMID 25562519, 2013). "The canonical Wnt signaling and the proinflammatory cytokine TNF-α play critical roles in development, homeostasis, and cancer." (PMID 24286133, 2013). "In cancer patients, the circulating levels of TNF-α and IFN-γ would be lower than the amounts used in this study." (PMID 24302570, 2013). "It is activated by insulin, glucocorticoids, tumor necrosis factor-alpha (TNFα), and estrogens and induces cancer progression by activation of the JAK2/STAT3, PI3K, and MAPK pathways through LEPR-B." (PMID 23819063, 2013). "To explore the involvement of TNF and IL-1, we added anti-TNFα neutralizing antibody and IL-1RA to the cancer cell–conditioned media prior to fibroblast stimulation." (PMID 23593346, 2013). "Collectively, Ssd was found to have an additive or synergistic effect with TNF-α for inducing cell death in both HeLa and HepG2 cancer cells." (PMID 23573150, 2013). "Tumor Necrosis Factor (TNF) is a mediator pro-inflammatory cytokine involved in the progression and development of cancer." (PMID 23724937, 2013). "Firstly, we used TNF to clearly demonstrate the inhibitory effects on the genes involved in cancer cell survival, proliferation, invasion, EMT, and angiogenesis." (PMID 23864892, 2013). "TNF-alpha increases CXCL1 and CXCL2 expression in cancer cells and amplifies the CXCL1/2 S100A8/9 loop, which causes chemoresistance." (PMID 25562519, 2013). "TNFα released from macrophages activates NF-κB-mediated signaling pathway in cancer, resulting in cancer progression and metastasis." (PMID 23818931, 2013). "All findings shed light on the potential usage of Ssd as a candidate adjuvant agent together with TNF-α for anti-cancer therapy." (PMID 23573150, 2013). "In the absence of doxorubicin, silencing or inhibiting c-Abl or Arg inhibited p65 nuclear localization, and decreased basal and TNF-α-induced NF-κB transcriptional activity, indicating that c-Abl/Arg activate NF-κB signaling in cancer cells." (PMID 23383209, 2013). "It is important to note that IL-6 and IL-10, TNF-α, and IL-1β have been implied in the generation of the MDSCs, which are commonly found in cancer patients." (PMID 23616009, 2013). "Several cancer therapies exploiting the cytotoxic effect of TNF-α on solid tumors and soft-tissue sarcomas have recently been examined in clinical trials." (PMID 23339680, 2013).
cancer (continued). "Until a decade ago, many researchers suggested introducing TNFα as a therapeutic agent in cancer because of its cytotoxic activities." (PMID 24369447, 2013). "Many cancer cell lines are resistant to TNF-induced cell death because NF-κB enhances the transcription of antiapoptotic proteins that interfere with death signaling, and TNF indeed augments cell proliferation in some of the cancer cells." (PMID 23864892, 2013). "Elevated circulating levels of inflammatory biomarkers, i.e., IL6, TNFα, C-reactive protein (CRP), have been associated with a greater risk for several types of cancer and cancer prognosis, including breast." (PMID 23991131, 2013). "Tumor necrosis factor (TNF) is a highly pleiotropic cytokine that plays a key role in inflammation, defense against microbial pathogens and cancer." (PMID 23833663, 2013). "GTCs are widely recognized to exert cancer-preventive effects partly by inhibiting the expression of TNF-α and IL-6, indicating that the suppression of inflammation is one of the key mechanisms by which GTCs prevent cancer development." (PMID 25674420, 2013). "Other studies also reported that antioxidants dose-dependently inhibit inflammatory markers like TNF-α, IL-6, and IL1β gene expression in the cells of chronic diseases and their release from a human cancer cell line." (PMID 23365614, 2013). "Since tumors are possible sources for inflammatory cytokines like IL-6 and TNF-α, analyses were repeated after excluding 8 patients who developed cancers within one year from baseline, to reduce the effect of a preclinical malignancy." (PMID 24205276, 2013). "In contrast, an inverse correlation between the inflammatory infiltrate and the expression of epithelial TNF-α was observed in carcinomas." (PMID 23833665, 2013). "Analysis of the relationship between the concentration of TNF-α and the variances of cancer-related fatigue using linear regression found that they have linear correlation." (PMID 22203880, 2012). "Many pathways were perturbed in almost all the cancers, with p-value less than 0.01: IL-3 pathway, IL-2 pathway, TNF-alpha Pathway EGFR1 pathway, TGF-beta receptor pathway, Alpha6 Beta4 Integrin pathway, and B Cell Receptor pathway." (PMID 22536907, 2012). "Although TNFα can be a potent death-inducing factor of cancer cells, its killing effects are often antagonized by its survival function that is mainly mediated by activation of the NF-κB and PI3K/AKT pathways." (PMID 22545132, 2012). "The combination of TNFα and triptolide results in stimulation of both extrinsic and intrinsic apoptotic pathways, thus contributing to greater apoptotic effect in cancer cells." (PMID 22545132, 2012). "Fenugreek blocked activation of NF-KB, I kappa B kinase and AKT and suppressed the production of various proinflammatory cytokines like IL-6, IL-1 and TNF-α by cancer cells." (PMID 23110539, 2012). "In an exploratory analysis of proinflammatory cytokines, markers of cancer-related fatigue, the mean serum concentrations of TNF-α pre- and posttreatment in experimental group were 128.70 pg/mL and 71.89 pg/mL." (PMID 22203880, 2012). "Leptin has pro-inflammatory properties and stimulates the growth of certain cancer cells as well as circulating pro-inflammatory cytokines, such as TNF-α and interleukin." (PMID 22666399, 2012). "Pooling all the treatment arms (i.e. whatever the dose), 94 cancers occurred on TNF-α antagonist and 30 on placebo." (PMID 23155441, 2012). "Despite this, when cancer cells were added to a monolayer of mesothelial cells that had been pretreated with TNFα, the cancer cells attached to the intracellular gaps where the sub-mesothelial collagen I matrix was exposed rather than to the mesothelial cells." (PMID 22527451, 2012). "From the ELISA consequence of cytokines as markers of cancer-related fatigue, the concentrations of TNF-α and IL-6 after treatment were significant lower than these before treatment." (PMID 22203880, 2012).
cancer (continued). "We previously demonstrated that p68 phosphorylation at threonine residues correlates with cancer cell apoptosis under the treatments of TNF-α and TRAIL (Yang, L. Mol Cancer Res Vol 3, pp 355–63 2005)." (PMID 23110695, 2012). "Recent reports further demonstrate in human cancer cell lines that spontaneous EMT or TGFβ/TNFα-mediated EMT generates cells with a claudin-low phenotype." (PMID 22654675, 2012). "Although IL6 is a well characterized inflammatory target gene for TNF-α, and bleomycin-induced fibrosis is ameliorated in Tnfr−/− mice, B cell infiltrates also fuel IL-6-mediated and Stat3-dependent cancer growth following the release of lymphotoxin (LT)." (PMID 22684844, 2012). "Our findings further question the utility of administering docetaxel to cancer patients on TNF-α blockers for treatment of co-morbid inflammatory diseases." (PMID 22225778, 2012). "Tumor necrosis factor alpha (TNF) is able to kill cancer cells via receptor-mediated cell death requiring adenosine triphosphate (ATP)." (PMID 23272249, 2012). "Tumor necrosis factor-α (TNF-α) is a pro-inflammatory cytokine involved in the promotion and progression of cancer." (PMID 23263670, 2012). "Over expression of miR-23a ~ 27a ~ 24-2 sensitized HEK293T cells to TNF-α cytotoxicity suggesting it to be of value in cancer therapy." (PMID 22954303, 2012). "Initially considered as a cytokine resulting in hemorrhagic necrosis of experimental cancers, TNF was later found to exert protumoral functions." (PMID 22811589, 2012). "In small, unrandomized clinical trials, thalidomide, a TNF-α inhibitor, has been shown to improve some cancer-ACS symptoms." (PMID 22518191, 2012). "It is therefore possible that the activity of cryptopleurine potentiates TNF-α-induced caspases activity and cancer cell death, at least in part, via its NF-κB inhibition." (PMID 22768286, 2012). "We believe that further study on PML and TNFα target genes will shed a light on specific molecular mechanisms of angiogenesis in cancer and human cardiovascular diseases." (PMID 22947142, 2012). "The T-cell mediated recognition of IDOlong was additionally analyzed by intracellular cytokine stainings (ICS) (IFN-γ, TNF-α, IL-17) in six cancer patients." (PMID 22539948, 2012). "Although, we were able to detect both IFN-γ and TNF-α response towards IDOlong in healthy donors, the responses were more frequent in cancer patients." (PMID 22539948, 2012). "TNFα is highly expressed by cancer and inflammatory cells, and its levels are elevated in peritoneal effusions of ovarian cancer patients." (PMID 22527451, 2012). "Evidence showed that TNFAIP8 expression was upregulated by TNF-α induced NF-κB pathway activation in cancer cell lines, which can inhibit caspase-8 and reduce apoptosis." (PMID 22666399, 2012). "When transcription is inhibited, TNF can induce apoptosis even in the most apoptosis-reluctant cells, a goal of cancer therapy (see the next section)." (PMID 22802145, 2012). "Both, TNF-α and IL-6 levels increased from Group 1 to Group 3 corresponding to increasing age and stages of cancer progression." (PMID 22427843, 2012). "It has long been thought that prolonged exposure to TNF-α contributes to cachexia in cancer patients." (PMID 22708547, 2012). "In cancer cells, activation of the apoptotic machinery by death receptor ligands of the tumor necrosis factor (TNF) superfamily of cytokines represents a novel therapeutic strategy." (PMID 23027370, 2012). "Copper N-(2-hydroxyacetophenone) glycinate is an interesting immunomodulatory agent, capable of inducing apoptosis in multidrug-resistant cancer cells by stimulating production of cytokines, such as interferon γ or TNF-α (Tumor Necrosis Factor α)." (PMID 22914969, 2012). "A wide variety of evidence has pointed to a critical role of TNF-α and the NF-κB pathway on cancer cell survival, proliferation, invasion, and angiogenesis." (PMID 22768286, 2012).
cancer (continued). "Cancer-induced muscle wasting is thought to be related to strongly increased circulating levels of pro-inflammatory cytokines, particularly TNF-α." (PMID 22257771, 2012). "A main anti-cancer effect of bortezomib is inhibition of NF-κB activation induced by TNF-α or TRAIL via blockade of I-κα degradation." (PMID 22393418, 2012). "Cytokines such as interferons, interleukin and tumor necrosis factor have been widely tested in the treatment of cancer." (PMID 21686188, 2011). "Tumor necrosis factor-related apoptosis-inducing ligand (TRAIL) is a member of the tumor necrosis factor (TNF) superfamily, which includes potent inducers of apoptosis in a wide variety of cancer cells." (PMID 21801359, 2011). "Administration of andrographolide led to enhanced production of TNF-α and expression of CD markers, eventually increasing the cytotoxic activity of lymphocytes against cancer cells." (PMID 19752167, 2011). "Activated Akt was implicated in proliferation/survival of PC cells and/or resistance to TNF-α mediated cell death in various cancers." (PMID 21880146, 2011). "In human cancer cachexia, a variety of cytokine levels is elevated with TNF-α being the key cytokine." (PMID 21637823, 2011). "TNF-α is an important inflammatory factor that acts as a master switch in establishing an intricate link between inflammation and cancer." (PMID 22029602, 2011). "The dysregulation of gene expression in the TNF-TNFR superfamily has been involved in various human cancers including non-small cell lung cancer (NSCLC)." (PMID 21995493, 2011). "Some cytokines, including Interleukin (IL)-2, Granulocyte-Macrophage Colony-Stimulating Factor (GM-CSF), Tumor Necrosis Factor alpha (TNF-α), and IL-12, have been demonstrated to induce desirable clinical responses in cancer patients." (PMID 24212958, 2011). "Especially MnSOD has been shown to be upregulated by NF-κB and to suppress TNFα-mediated ROS accumulation and cell death in MEFs and cancer cells." (PMID 21533085, 2011). "Our data from ex vivo cultured ileal biopsies of otherwise healthy individuals undergoing endoscopy for cancer surveillance suggested that TNFα-induced NOD2 expression was also reduced by CSE." (PMID 21931826, 2011). "In contrast, treatment with TNFα only resulted in an increased migration capacity of rat astrocytes as observed in other cell types, including cancer cells and mesenchymal stem cells." (PMID 21949843, 2011). "A recent work demonstrates that tumor necrosis factor-α (TNF-α) related apoptosis inducing ligand (TRAIL—an important member of extrinsic apoptosis pathway) was significantly enhanced in various human cancer cell lines after treatment with andrographolide." (PMID 19752167, 2011). "Studies have ultimately attributed the abnormal activation of NF-κB in cancer cells to the excessive secretion of TNF-α, whose role in CXCR4 upregulation is subsequently assumed to be related to pathways mediated by NF-κB." (PMID 20699000, 2010). "Genetic polymorphisms of tumor necrosis factor (TNF) -α and its surface receptors, TNFRSF1A and TNFRSF1B have been examined in terms of susceptibility to various cancers." (PMID 20646319, 2010). "Clinically, HIV therapy and chemotherapy produce peripheral neuropathy with massive release of TNF-α in serum and TNF-α used as a clinical anti-cancer treatment leads to peripheral neuropathy." (PMID 20398373, 2010). "Results from IPA show that the signature genes interact with major cancer signaling pathways, such as TNF and AKT." (PMID 20808922, 2010). "In particular, large increases are expected for "biological" drugs, such as TNF-alpha inhibitors and monoclonal antibodies, and small molecules for targeted cancer therapy." (PMID 20478043, 2010). "TNFα is important in all steps of cancer development, for example, initiation, promotion, and survival." (PMID 20064207, 2010). "In 14 patients (ever exposed to anti-TNFα: eight, to anakinra: one) 15 recurrent cancers were observed." (PMID 20064207, 2010).
cancer (continued). "Reduced MyoD levels, but unchanged NF-κB DNA-binding, were detected in a TNFα-dependent experimental model of cancer cachexia." (PMID 21048967, 2010). "Our analysis also showed that TNF-α affects the pathway involved in neurological disease and organismal injury and nervous system development, cell cycle and cancer." (PMID 20967264, 2010). "Further, several studies have shown that ectopic expression of SPHK1 can protect cancer cells against apoptosis in response to pro-apoptotic stimuli, such as treatment with TNF-α, ionizing radiation, or anti-cancer drugs, through multiple pathways." (PMID 20846391, 2010). "Instead, we have demonstrated that some cancer cells depend on NF-κB signaling for proliferation (8505C), while others require it for invasion and resistance to TNFα-induced apoptosis (TPC1, SW1736)." (PMID 20492683, 2010). "The aim of this study, therefore, was to explore the influence of anti-TNF therapy on the incidence of cancer in patients with RA and prior malignancy." (PMID 20535785, 2010). "Increased levels of TNF-α have been observed under conditions that lead to skeletal muscle atrophy such as chronic heart failure, cancer, AIDS, and cachexia induced by bacteria." (PMID 20967264, 2010). "It renders cancer cells sensitive to the proapoptotic affects of TNF-α, suggesting that survivin blocks the extrinsic pathway of apoptosis." (PMID 20920299, 2010). "Combination of the biologically active dNSurR9-C84A protein or other survivin antagonists with TNF-α therapy warrants consideration as an approach to cancer therapy." (PMID 20920299, 2010). "TNF-α also has a role in cancer cachexia and fatigue and is a putative autocrine and paracrine growth factor in RCC." (PMID 20842130, 2010). "Along with NF-κB, factors such as TNF and interleukins (IL-1β, IL-6, and IL-8) also serve as connecting links between inflammation and cancer." (PMID 22069560, 2010). "Tumour necrosis factor-alpha (TNF-α) is an important inflammatory factor that acts as a master switch in establishing an intricate link between inflammation and cancer." (PMID 20087353, 2010). "Another possible imbalance was differential cancer screening prior to study entry between the cohorts treated with anti-TNF therapy and DMARDs." (PMID 20535785, 2010). "The TNF-α enhances the invasive property of cancer cells by inducing EMT through Snail- or ZEB1/ZEB2-dependent mechanisms." (PMID 20087353, 2010). "A large body of evidence signifies the role of inflammation in cancer development through mediators such as reactive oxygen species (ROS), free radicals, and inflammatory cytokines like tumor necrosis factor-α (TNFα), lymphotoxins, and angiogenic factors." (PMID 22069560, 2010). "The role of TNFα in cancer is complex with both pro-tumourigenic and anti-tumourigenic roles proposed." (PMID 20573209, 2010). "The expression of TNF-α was significantly up-regulated in cancer mice compared with that of sham control, as revealed by Western blot." (PMID 20923560, 2010). "Three patients developed a recurrent cancer less than five years after the previous cancer (two in the anti-TNFα treated group, one in the DMARD group)." (PMID 20064207, 2010). "Knockdown of Snail expression not only inhibits TNF-α-induced cancer cell migration and invasion in vitro but also suppresses LPS-mediated metastasis in vivo." (PMID 20087353, 2010). "Our interest is consequently drawn to its involvement in the induction of CXCR4 expression by H. pylori, a potent inducer of TNF-α, which is known to upregulate a series of cytokines, chemokines, adhesion molecules and growth factors in cancers." (PMID 20699000, 2010). "WWOX/WOX1 is known to increase the cytotoxic function of tumor necrosis factor (TNF) in killing cancer cells." (PMID 21212468, 2010). "In a nested case-control study comparing cancer patients to cancer-free controls, 44 of the cancer patients and 44 of the cancer-free controls were ever exposed to anti-TNFα agents (P = 1.0)." (PMID 20064207, 2010).